MIR3131 (microRNA 3131)
Synonyms: hsa-mir-3131; mir-3131
Gene: MicroRNA gene on chromosome 2 (219,058,688 to 219,058,750, reverse strand). Ensembl gene ENSG00000264755.
Diseases named in the same sentence as MIR3131 in open-access papers:
MIR3131 is named in the same sentence as 1 disease in open-access papers, as found by Europe PMC text mining. Sharing a sentence is not in itself a finding about the gene and the disease.
MIR3131 shares sentences with these, for which no sentence is quoted: cancer (1 paper).